SULT1A2 (sulfotransferase family 1A member 2)
Description:
Sulfotransferase that utilizes 3'-phospho-5'-adenylyl sulfate (PAPS) as sulfonate donor to catalyze the sulfate conjugation of catecholamines, phenolic drugs and neurotransmitters. Is also responsible for the sulfonation and activation of minoxidil. Mediates the metabolic activation of carcinogenic N-hydroxyarylamines to DNA binding products and could so participate as modulating factor of cancer risk.
Synonyms: ST1A2; P-PST 2; STP2; HAST4; P-PST; TSPST2
Tractability: Small molecule: a structure with a bound ligand is known; it has a high-quality binding pocket. PROTAC: ubiquitination databases record sites on it.
Target class: Enzyme; Transferase
Gene: Protein-coding gene on chromosome 16 (28,591,790 to 28,599,913, reverse strand). Ensembl gene ENSG00000197165.
Subcellular location: Cytoplasm
Pathways (Reactome):
Metabolism: Cytosolic sulfonation of small molecules
Gene Ontology:
Molecular function: aryl sulfotransferase activity; flavonol 3-sulfotransferase activity; protein binding; sulfotransferase activity
Biological process: 3'-phosphoadenosine 5'-phosphosulfate metabolic process; ethanol catabolic process; phenol-containing compound metabolic process; sulfation; xenobiotic metabolic process; amine biosynthetic process; sulfur compound metabolic process
Cellular component: cytosol; cytoplasm
Genetic constraint (gnomAD): Loss-of-function variants: 33 observed, 35.66 expected, observed/expected ratio (o/e) 0.93, 90% interval 0.7 to 1.24. The upper end of that interval is the gene's LOEUF score, 1.24, which puts it in group 5 of 6, group 1 being the genes least tolerant of losing a copy. Missense variants: 367 observed, 389.11 expected, observed/expected ratio (o/e) 0.94, 90% interval 0.87 to 1.03. Synonymous variants: 138 observed, 144.06 expected, observed/expected ratio (o/e) 0.96, 90% interval 0.83 to 1.1.
Homologues: Orthologues: chimpanzee SULT1A2 (98% identical), tropical clawed frog sult1b1 (51% identical), zebrafish sult1st3 (48% identical), zebrafish sult1st1 (48% identical), zebrafish sult1st2 (48% identical), zebrafish sult1st7 (48% identical), zebrafish sult1st9 (48% identical), zebrafish sult1st4 (46% identical), tropical clawed frog sult5a1 (39% identical), zebrafish sult5a1 (39% identical), zebrafish sult2st1 (37% identical), zebrafish sult2st2 (37% identical), and 7 more. Paralogues in human: SULT1A1 (96% identical), SULT1A3 (90% identical), SULT1A4 (90% identical), SULT1C4 (54% identical), SULT1B1 (54% identical), SULT1C2 (51% identical), SULT1C3 (49% identical), SULT1E1 (49% identical), SULT2A1 (36% identical), SULT2B1 (35% identical), SULT4A1 (34% identical), SULT6B1 (31% identical).
Diseases named in the same sentence as SULT1A2 in open-access papers:
SULT1A2 is named in the same sentence as 20 diseases in open-access papers, as found by Europe PMC text mining. Sharing a sentence is not in itself a finding about the gene and the disease. The quoted sentences say what the papers report.
breast carcinoma (9 papers, 2013 to 2023). "The risk regulation of SULT1A2 on HER2-positive breast cancer and its relevance to treatment need to be further explored." (PMID 35663326, 2022). "Our results show that low expression of SULT1A2 is associated with improved survival in HER2-positive breast cancer." (PMID 35663326, 2022). "SULT1A2 which drastically reduces its affinity for the substrate, is supposed to be associated with bladder cancer and breast cancer." (PMID 28099906, 2017). "Finally, we showed that increased expression of the human enzymes that form IS (Cyp2E1, Sult1A1, and Sult1A2) is associated with better survival in breast cancer, an effect that is lost in triple negative cases." (PMID 33050543, 2020). "In addition, a study of 230 breast cancer patients in Taiwan found that SULT1A2 gene polymorphism may be associated with the early onset of breast cancer patients." (PMID 37142702, 2023). "Higher expression of Cp2E1 and Sult1A1 and Sult1A2 in tumors correlated with better survival in breast cancer patients." (PMID 33050543, 2020). "SULT1A2 encodes phenol sulfotransferases involved in hormone metabolism and has been reported to be associated with the prognosis of patients with HER2-positive breast cancer." (PMID 36761027, 2023). "Importantly, in HER2-positive breast cancer, decreased expression of metabolism-related genes ATIC, HPRT1, ASNS, SULT1A2, and HAL was associated with increased survival." (PMID 35663326, 2022). "However, BMI was the only breast cancer risk factor influencing fluxes to adducts of estrogens with DNA, probably by increasing levels of CYP1B1 and/or decreasing those of SULT1A2 in addition to increasing estrogen levels." (PMID 34921608, 2022). "Compared with normal control tissues, the expression of HPRT1, ASNS, ATIC, SULT1A2, and HAL was significantly increased in HER2-positive breast cancer samples." (PMID 35663326, 2022). "In this descriptive study, correlations were examined between concentrations of tamoxifen metabolites and genotypes for CYP2D6, CYP3A4, CYP3A5, SULT1A1, SULT1A2 and SULT1E1 in 135 patients with estrogen receptor-positive breast cancer." (PMID 23922954, 2013). "In addition, ATIC, HPRT1, ASNS, SULT1A2, and HAL may represent attractive therapeutic targets for HER2-positive breast cancer, and require further validation studies, especially considering that treatment with specific inhibitors may alter the expression of these metabolic genes." (PMID 35663326, 2022). "We found that the expression of the members of detoxification enzyme sulfotransferase family SULT1A1 and SULT1A2, but not other SULT family members, was induced in the metastatic breast cancers as compared to the primary tumors." (PMID 32727562, 2020).
Obesity (7 papers, 2015 to 2025). Accumulation of substantial excess body fat. "It has been found that a nonsynonymous mutation rs141581853 (P. Arg 213 His) in the SULT1A1 gene is associated with human obesity, and this locus is linked to SULT1A2 rs10594919." (PMID 37142702, 2023). "For the first time, we found an association between the coding variant rs1059491 in the SULT1A2 gene and obesity risk in adults, which laid a foundation for further research on gene function and the molecular mechanism of obesity." (PMID 37142702, 2023). "In conclusion, this study revealed that the coding variant rs1059491 in the SULT1A2 gene is nominally associated with a decreased risk of obesity and dyslipidaemia in southern Chinese adults." (PMID 37142702, 2023). "The indirect evidence supported the association of the coding variantrs1059491 in SULT1A2 with the risk of obesity and dyslipidaemia." (PMID 37142702, 2023). "Obesity is associated with increased levels of 17-β-estradiol, estron and estron sulfate which are substrates of SULT1A2." (PMID 25955518, 2015). "The SULT1A2 (sulfotransferase family, cytosolic, 1A, phenols-preferring, member 2) gene is located at 16p12.1, which is close to 16p11.2, a popular region in obesity research." (PMID 37142702, 2023). "The Chr16p11 gene set consists of 212 genes, some of which are associated with obesity, including SH2B1, APOBR, SULT1A1, SULT1A2, and TUFM." (PMID 29854750, 2018). "In order to fine map the chromosomal region chr16p11.2 for further obesity associated variants, we screened the coding regions of APOBR, SULT1A1, SULT1A2, and TUFM for variants in 95 extremely obese children and adolescents." (PMID 25955518, 2015). "Previous fine mapping studies of obesity candidate genes in the 16p11.2 region indicated that rare mutations in nearby genes APOBR12 and SH2B118 but not SULT1A2 were strongly associated with the risk of obesity or extreme obesity." (PMID 37142702, 2023). "In SULT1A2, none of the variants was associated with obesity, so they do not contribute to our initial TDT finding although some of the variants were predicted to have functional effects." (PMID 25955518, 2015). "None of the analyzed non-synonymous SNPs in SULT1A2 showed association with obesity in 355 obesity trios (TDT)." (PMID 25955518, 2015). "Carriers of the rs1059491G allele in the sulfotransferase family 1A member 2 (SULT1A2) gene exhibited a 54% reduction in overweight/obesity risk compared to non-carriers, a phenomenon potentially mediated through its location within the PPARγ2 and RXRA transcription factor binding sites." (PMID 41340654, 2025). "To date, whether SULT1A2 rs1059491 is associated with adulthood obesity and related cardiometabolic risk factors has not been reported in China." (PMID 37142702, 2023). "Moreover, there was no significant influence of the genotype of SULT1A2 rs1059491 on obesity-related phenotypic traits, including weight, SBP, DBP, TC, HDL-C, LDL-C, and FPG." (PMID 37142702, 2023).
bladder cancer (2 papers, 2017 to 2025). "Compared with normal bladder tissues (ANBTs), the expression of SULT1A2 in bladder cancer tissues is higher." (PMID 40423332, 2025).
diabetes (2 papers, 2019 to 2021). "For example, streptozotocin affects the proteins encoded by TH and SULT1A2, and has been widely used experimentally to induce diabetes in rodent models due to its toxic effects on pancreatic beta cells." (PMID 34230558, 2021).
infection (5 papers, 2011 to 2025). The state of being infected such as from the introduction of a foreign agent such as serum, vaccine, antigenic substance or organism. "However, the effects of ADGB and SULT1A2 in infection and immune responses remain to be clarified." (PMID 38020709, 2023).
cancer (2 papers, 2015 to 2023). A tumor composed of atypical neoplastic, often pleomorphic cells that invade other tissues. "Among these, sulfotransferases (SULT1A1, SULT1A2, SULT1A3) and aldo-keto reductases (AKR1C1, AKR1C2, AKR1C3) were shown to contribute to disease progression and/or represent therapeutic targets in hormone-dependent forms of cancer, including EOC." (PMID 26372729, 2015).
tumor (1 paper, 2020). "SULT1A2 (RI, 1.2:1.3) and CALD1 (ES, 8.3:9) exhibit the highest Δmedian PSI values between healthy and tumor tissues, in both left and right." (PMID 32293332, 2020).
SULT1A2 also shares sentences with these, for which no sentence is quoted: asthma (1 paper); autoimmune disease (1); Autoimmunity (1); dyslipidaemia (1); experimental autoimmune encephalomyelitis (1); fungal infections (1); heart disease (1); inflammatory bowel disease (1); lung carcinoma (1); Malignant neoplasm of bronchus (1); melanoma (1); pancreatic adenocarcinoma (1); pancreatic cancer (1).